SPINK1 (serine peptidase inhibitor Kazal type 1)
Diseases named in the same sentence as SPINK1 in open-access papers (continued):
Sharing a sentence is not in itself a finding about the gene and the disease.
cancer (continued). "Third, an important step of cancer evolution, neoangiogenesis, emerged upon the treatment of cancer cells with stromal SPINK1." (PMID 30333494, 2018). "Although well-validated assays of soluble factors are developed, comprehensive subtyping using SPINK1-based assays for pan-cancer investigation remains an unexplored but exciting area in translational medicine." (PMID 30333494, 2018). "We established that miR‐338‐5p and miR‐421 mediate several cellular responses against SPINK1‐positive cancer by inducing S‐phase cell‐cycle arrest, inhibiting epithelial‐to‐mesenchymal transition (EMT), cancer stemness and drug resistance." (PMID 29460395, 2018). "Of note, Cox proportional hazard regression analyses of these patients indicated a significant correlation of stromal SPINK1 with poor cancer survival." (PMID 30333494, 2018). "Immunostaining of SPINK1 was coincident with the defined cancer region and immunostaining of NPY was mostly localized to that of the PIN region." (PMID 29925878, 2018). "In vivo, SPINK1 is expressed in the stroma of solid tumours and is routinely detectable in peripheral blood of cancer patients after chemotherapy." (PMID 30333494, 2018). "Known PCa-related genes (SPON2, TFF3, SPINK1) are among the highest-expressed genes in the “cancer” factor." (PMID 29925878, 2018). "Beyond basal expression in pancreatic acinar cells, SPINK1 is diagnosed in multiple human cancer types and correlated with adverse clinical outcomes." (PMID 30333494, 2018). "Our data suggest the development of an in vivo SASP, the index of which can be measured by quantifying the concurrently expressed soluble factors including but not limited to SPINK1 and IL-8 in the peripheral flood of post-treatment cancer patients." (PMID 30333494, 2018). "SPINK1 (serine peptidase inhibitor, Kazal type 1) overexpression has been identified in many cancers including the colon, lung, breast and prostate." (PMID 26258891, 2015). "SPINK1 is a soluble factor secreted by cancer cells, and we anticipate that its effects on proliferation are likely to be mediated through an autocrine signaling pathway." (PMID 26437224, 2015). "On the other hand, SPP1, SPINK1 and STEAP1 are proteins that are up-regulated in several human carcinomas and their overexpression is also associated to cancer progression." (PMID 24865347, 2014). "By contrast, SPINK1 itself has been shown to have growth factor activity in various cell lines, including certain cancer cells." (PMID 24932227, 2014). "Gene expression profiling analysis identified SPP1, CTHRC1and GREM1 as potential biomarkers for early diagnosis of the cancer, and SPINK1 and BMP7 to distinguish between AC and SCC in small biopsies or in blood samples." (PMID 24299561, 2013). "SPINK1 is also overexpressed in other cancers, and an elevated serum level is an independent prognostic indicator in many of these, as reviewed by Paju and Paju." (PMID 24281110, 2010). "This suggests that SPINK1 may drive malignant progression through similar inflammatory mechanisms in other cancers." (PMID 40904507, 2025). "Additionally, the SPINK1 gene is linked to a favorable prognosis in CRC patients, as reported in a study investigating its functional role in cancer." (PMID 41465391, 2025). "SPINK1, serine protease inhibitor Kazal type ɪ, is an autocrine or paracrine protein that is linked to the senescence-associated secretory phenotype (SASP) and cancer progression." (PMID 38693111, 2024). "SPINK1 expression was predominantly observed in a subgroup of cancers that expressed TFF3." (PMID 38256434, 2024). "SPINK1 expression was predominantly observed in a subgroup of cancers that expressed TFF3 (6/6)." (PMID 38256434, 2024). "Our findings reveal that SPINK1 expression was predominantly observed in a subgroup of cancers that expressed TFF3 (n = 6/6, p-value 0.013 highlighting the potential significance of assessing both TFF3 and SPINK1 statuses in order to stratify the risk of PCa patients." (PMID 38256434, 2024).
cancer (continued). "We found knockdown of REG4 or SPINK1 do alter a series of cancer-related characteristics in PDAC." (PMID 38827297, 2024). "SPINK1, which has previously been found to be overexpressed in HBV and HCV-related HCC and associated with different cancer types, has been reported to promote cell proliferation, increase metastatic and invasive potential, and hold promise as a potential diagnostic marker." (PMID 38030644, 2023). "Targeting SPINK1 may widen the therapeutic window for combating chemoresistant cancer stemness in the clinic." (PMID 38030644, 2023). "Many studies have been conducted to investigate the predictive value of SPINK1 in cancer." (PMID 38093163, 2023). "Likewise, overexpression of SPINK1 (also known as tumor-associated trypsin inhibitor, TATI) has been linked to the expansion of many malignant tumors, including the HCC, as it favors cancer cells proliferation, metastasis, and anticancer drug resistance." (PMID 37894381, 2023). "Recent studies have shown that SPINK1 has an important prognostic role in development of many cancers and could be targeted therapeutically." (PMID 36053457, 2022). "Moreover, our study will simultaneously provide some new thoughts and hints for deep exploration of SPINK1-related molecular mechanisms involved in the pathogenesis of other types of cancers." (PMID 37305325, 2022). "SPINK1 is highly expressed and contributes to cancer progress in multiple cancers, including HCC." (PMID 35747248, 2022). "In addition, it is known that SPINK1 downregulates metallothionein gene expressions, and therefore metallothionein genes that are involved in the SPINK1 general cancer pathway listed in this study’s IPA canonical pathway analysis." (PMID 35369880, 2022). "Even under normoxic conditions, secreted SPINK1 protein enhances the radiation tolerance of cancer cells in a manner dependent on epidermal growth factor receptor (EGFR) and nuclear factor erythroid 2 related factor 2 (NRF2) and accelerates the growth of tumors after radiotherapy." (PMID 35223512, 2022). "Aggressiveness and recurrence were also correlated with high SPINK1 expression in other cancers." (PMID 36053457, 2022). "For instance, among the genes specifically detected in MAY, SPINK1 promotes the progression of various types of cancer and is involved in abnormal morphology of thin skin." (PMID 35137043, 2022). "Though SPINK1 has been known to be a negative regulator of autophagy in normal murine pancreatic cells, the connection between SPINK1 and autophagy remains unknown on different cancer cells." (PMID 37305325, 2022). "Emerging evidence has demonstrated the relationship between SPINK1 and cancer progression." (PMID 33916984, 2021). "SPINK1 induces the epithelial-mesenchymal transition, cellular plasticity, and cancer stemness." (PMID 33916984, 2021). "IPA predicted the activation of the SPINK1 General Cancer Pathway (z = 2.53) in the A549/DDP cells." (PMID 33753779, 2021). "First, we examined whether SPINK1 protein is expressed in hypoxic regions and secreted to the surrounding and oxygenated regions in human cancers by performing IHC analysis." (PMID 34747365, 2021). "In addition to the biological function of SPINK1 in cancer, its clinical and prognostic significance in multiple cancer types is demonstrated." (PMID 33916984, 2021). "The role of SPINK1 in modulating cancer cell proliferation has been reported." (PMID 33916984, 2021). "Moreover, the SPINK1-mediated cancer radioresistance was completely abrogated by a SPINK1-neutralizing antibody." (PMID 34747365, 2021). "In addition, a comprehensive summary of SPINK1 expression in a pan-cancer panel and individual cell types of specific organs at the single-cell level is presented to indicate the potential sites of tumorigenesis, which has not yet been reported." (PMID 33916984, 2021). "Studies have evaluated the prognostic significance of SPINK1 in cancer." (PMID 33916984, 2021).
cancer (continued). "Finally, we examined the involvement of the Nrf2-related expression of antioxidant genes in SPINK1-dependent cancer radioresistance." (PMID 34747365, 2021). "Several studies have revealed the role of SPINK1 in drug resistance in cancer." (PMID 33916984, 2021). "Emerging findings further clarify the direct and indirect biological effects of SPINK1 in regulating cancer proliferation, metastasis, drug resistance, transdifferentiation, and cancer stemness, warranting the exploration of the SPINK1-mediated molecular mechanism to identify a therapeutic strategy." (PMID 33916984, 2021). "Moreover, we demonstrated that SPINK1 secreted from hypoxic cancer cells has the potential to induce radioresistance of the surrounding oxygenated cells in a paracrine manner through activation of the EGFR-mediated and Nrf2-mediated antioxidant pathway." (PMID 34747365, 2021). "Outside of the normal pancreas, aberrant expression of SPINK1 plays a role in cancer." (PMID 30778387, 2019). "We suggest that efforts to more clearly confirm or identify the direct receptor of SPINK1, and the mechanism by which it influences EGFR signaling, could lead to identification of novel points for therapeutic intervention in cancers that express SPINK1." (PMID 30778387, 2019). "Moreover, ectopic expression of miR‐338‐5p and miR‐421 in SPINK1‐positive PCa cells attenuate oncogenic properties, epithelial‐to‐mesenchymal transition and cancer stemness." (PMID 29460395, 2018). "We then interrogated whether the amount of SPINK1 circulating in the serum is correlated with that of other typical SASP factors such as IL-8 in a same individual patient after cancer treatment." (PMID 30333494, 2018). "Given the effects of SPINK1 on cancer cell properties in vitro, we next interrogated whether SPINK1 generates any pathological consequences in vivo." (PMID 30333494, 2018). "We next sought to assess whether SPINK1 is experimentally detectable in the circulating system of cancer patients post-chemotherapy." (PMID 30333494, 2018). "In the cancer region we for instance observe enrichment of SPINK1 and PGC, and depletion of ACPP." (PMID 29925878, 2018). "Thus, SPINK1 induced a striking epithelial-to-endothelial transition (hereby termed EET), suggesting a salient capacity of paracrine SPINK1 in reprogramming the transcriptome of recipient cancer cells." (PMID 30333494, 2018). "Although PSC27-BLEO CM increased the viability of PC3 exposed to MIT at 0.1–1.0 μM, a range of dose close to its serum concentrations in cancer patients, SPINK1-neutralization offset cancer resistance in a similar way as SPINK1 mAb was co-applied with cetuximab (P < 0.01)." (PMID 30333494, 2018). "Contrasting the limited therapeutic effect of SPINK1-targeting agents projected for SPINK1+ individuals in PCa patients, SPINK1 mAb-based therapies against the TME take advantage of circumventing the need to stratify cancer patients according to any molecularly defined attributes." (PMID 30333494, 2018). "In contrast, routine surveillance of SPINK1 in post-treatment individuals through a noninvasive route such as liquid biopsy provides a novel, handy, and precise strategy for both prognosis and prevention of advanced pathologies in future cancer medicine." (PMID 30333494, 2018). "Likewise, cancer cells were significantly protected from anoikis at SPINK1 concentrations as low as 10 pM." (PMID 26437224, 2015). "We found that CBX7 negatively or positively regulates the expression of several genes (such as SPP1, SPINK1, STEAP1, and FOS, FOSB, EGR1, respectively) associated to cancer progression, by interacting with their promoter regions and modulating their transcriptional activity." (PMID 24865347, 2014). "SPINK1 is aberrantly expressed in a number of different cancers." (PMID 23527199, 2013). "SPINK1 over-expression may promote invasion and metastasis of cancer cells through a number of potential mechanisms." (PMID 23527199, 2013).
cancer (continued). "Detection of circulating SPINK1 protein or mRNA has been described in a number of cancers." (PMID 23527199, 2013). "Moreover, our data may prove useful in the field of cancer research, as the roles of SPINK1 in EGFR binding and granzyme A inhibition are still poorly understood." (PMID 35408828, 2022). "In addition, because SPINK1 proteins were found to diffuse from hypoxic areas toward relatively oxygenated layers, our data collectively indicate that SPINK1 proteins secreted by cancer cells in hypoxic layers protected neighboring cancer cells in the relatively oxygenated layers from radiation." (PMID 34747365, 2021). "However, our results suggest that the clinicopathological significance of ERG/SPINK1 status is different between TZ and PZ cancer cases, thereby suggesting the presence of different genetic alterations in the carcinogenesis and progression in both types of cancers." (PMID 35475132, 2021). "In addition, the regulatory mechanism of SPINK1 expression in cancer types has been reported." (PMID 33916984, 2021). "However, whether those mutant forms of SPINK1 are independent factors of cancer remains to be explored." (PMID 33916984, 2021). "Moreover, SPINK1 is also shown to play a role in cancer cell survival and progression." (PMID 32195182, 2020). "However, SPINK1 overexpression, which was observed in different types of cancer, may be partially due to SPINK1 having structural homology with the epidermal growth factor." (PMID 31886233, 2019). "Thus, restoring miR‐338‐5p and miR‐421 expression using either epigenetic drugs or synthetic mimics could abrogate SPINK1‐mediated oncogenesis by targeting multiple oncogenic pathways and eliciting anti‐cancer pleiotropic effects." (PMID 29460395, 2018). "Western blot confirmed increased SPINK1 protein levels in OSCC cells, aligning with its oncogenic roles in other cancers." (PMID 40904507, 2025). "DEG analysis revealed higher expression levels of CRC markers such as CEACAM6, SPINK1, TGFBI and RSPO3 in the cancer cell group." (PMID 40355592, 2025). "A number of SASP components including WNT16B, SFRP2, SPINK1, and AREG display strong capacity in conferring resistance to cancer cells." (PMID 37475161, 2024). "SPINK1, a SASP that exhibits EGF-like traits, is pivotal in regulating cancer progression, including stemness, proliferation, metastasis, and drug resistance." (PMID 38693111, 2024). "To functionally characterize the importance of EGFR in mediating the cancer stemness properties directed by SPINK1, we treated HCC cells with recombinant SPINK1, in the absence or presence of EGFR knockdown or FDA-approved EGFR inhibitor, Erlotinib." (PMID 38030644, 2023). "This possibly pave a new avenue for understanding the molecular mechanisms which is likely responsible the roles of SPINK1 in the pathogenesis of CRC, even in other types of cancers." (PMID 37305325, 2022). "Firstly, we lacked clinical data with respect to the confirmed significance of the level of SPINK1 in serum for the early detection of patients with HCC, which is the most accessible and practical test in the laboratory for cancer assessment." (PMID 35924241, 2022). "We examined the correlation between the transcriptomic expression of SPINK1 and a number of critical ICPs—PD-1, LAG-3, TIM-3, TIGIT, and CTLA-4—which are the likely signatures for the response to ICB in cancer immunotherapy." (PMID 35924241, 2022). "The following showed that the accumulated data not only favorably supported the function of SPINK1 in the detection of HCC but also gradually led to the temporary conclusion that it may also be a possible molecular target in HCC therapies based on some of its unique biological features of cancer." (PMID 35924241, 2022). "Regarding the relationship between ERG/SPINK1 expression and clinicopathological parameters, among TZ cancers, ERG‐/SPINK + cases showed a significantly lower BCR‐free survival rate than ERG‐/SPINK1‐ cases." (PMID 35475132, 2021).
cancer (continued). "In the TZ cancer group, statistical analyses were conducted only between ERG‐/SPINK1‐ and ERG‐/SPINK1 + subgroups because of the extremely lower prevalence of ERG‐overexpression in this group." (PMID 35475132, 2021). "All of these data suggest that SPINK1 decreased radiation-induced DNA damage by upregulating EGFR-mediated and Nrf2-dependent antioxidant responses, and consequently induced cancer radioresistance." (PMID 34747365, 2021). "Here, we examined the immunohistochemical features of TZ and PZ cancers using three antibodies, ERG, PTEN, and SPINK1." (PMID 35475132, 2021). "Here, we explored the possibility of minimizing cancer resistance by targeting the major SASP factors which act as the most critical players in driving acquired resistance, with SPINK1 emerging as one of such targetable molecules." (PMID 30333494, 2018). "Here, the authors show that genotoxic stress induces senescence in human stromal cells, which in turn secrete serine protease inhibitor Kazal type 1 (SPINK1) and promote acquired resistance of cancer cells via EGFR-mediated paracrine signaling." (PMID 30333494, 2018). "In this study, we found stromal cell-derived SPINK1 not only activates Akt/mTOR, Mek/Erk/Stat3 pathways, signaling branches downstream of EGFR, but also generates profound impact on cancer cell transcriptomics." (PMID 30333494, 2018). "Among the genes that appeared down-regulated by CBX7 expression we focused on the SPP1, SPINK1 and STEAP1 genes since their expression has been found overexpressed in human carcinomas." (PMID 24865347, 2014). "Additionally, the SPINK1 pathway activates the NRF2 pathway, which leads to increased proliferation and decreased apoptosis of cancer cells." (PMID 35202241, 2022). "Treatment with the recombinant SPINK1 protein and the forced expression of SPINK1, but not that of SPINK1-ΔSP, significantly increased the viability of cancer cells after radiation in vitro, indicating that SPINK1 induced radioresistance in a paracrine manner." (PMID 34747365, 2021). "Hence, the interaction of SPINK1 with EGFR has attracted attention for its potentially pivotal biological functions, especially in modulating cancer progression." (PMID 33916984, 2021). "In contrast, among the PZ cancer cases, ERG‐/SPINK1‐ cases showed the highest GG (P = .0119)." (PMID 35475132, 2021). "A panel of SPINK1 positive and negative cancer cell lines were used to confirm the specificity of the SPINK1 antibody by immunostaining." (PMID 31959826, 2020). "We subsequently interrogated whether SPINK1, a soluble factor expressed in the entire SASP spectrum of stromal cells, plays a major role in shaping advanced cancer phenotypes." (PMID 30333494, 2018). "Furthermore, SPINK1 shares structural similarity with epidermal growth factor (EGF), an important growth factor in hepatocellular and many other cancers." (PMID 23527199, 2013). "Interestingly, SPINK1 has recently been shown to be up-regulated, in a mutually exclusive pattern, in a small percentage of TMPRSS2-ERG-negative carcinomas." (PMID 21814574, 2011). "In this respect, the recent observation that a proportion of ETS-gene rearrangement negative cancers overexpress SPINK1 protein is of particular interest." (PMID 20104229, 2010). "Furthermore, activation of the Spink1 general cancer pathway, as indicated by IPA analysis, is notable, as Spink1 increases cell proliferation via Pi3k and Akt58." (PMID 38600221, 2024). "Through comparing ‘HCC’ CD133+ and ‘normal’ CD133+ cells, we identify SPINK1 to be preferentially enriched in CD133 + HCC and to correlate with a poorly differentiated phenotype in mouse/human developing livers as well as aggressive cancer features in HCC clinical samples." (PMID 38030644, 2023).